INS (insulin)
Diseases named in the same sentence as INS in open-access papers (continued):
Sharing a sentence is not in itself a finding about the gene and the disease.
atherosclerosis (continued). "At the same time, KEGG pathway analysis provided evidence that the signaling pathways mainly involved the PPAR, AMPK pathways, insulin resistance, lipid and atherosclerosis, and alcoholic liver disease, among others." (PMID 41011216, 2025). "In both groups, enriched pathways were primarily related to signal transduction, cellular senescence, lipid metabolism and atherosclerosis, Th17 cell differentiation, insulin resistance, autophagy, and apoptosis." (PMID 41282288, 2025). "Experimental studies using small-molecule NNMT inhibitors and RNA interference have shown promising cardiometabolic benefits in preclinical models, including improved insulin sensitivity, reduced atherosclerosis, and attenuated cardiac dysfunction." (PMID 41008588, 2025). "In animal models, selenoprotein deficiency leads to increased susceptibility to inflammation and oxidative stress, which can drive chronic conditions like atherosclerosis and insulin resistance—key comorbidities of frailty." (PMID 40791232, 2025). "In contrast, mice overexpressing IRS1, specifically in VECs, increased insulin signaling and reduced atherosclerosis." (PMID 40141412, 2025). "While it promotes inflammation in atherosclerosis, liver fibrosis, and inflammatory airway disorders, it also supports astrocyte survival and regulates insulin secretion in the hypothalamus." (PMID 40986444, 2025). "SGLT2is exert pleiotropic anti-inflammatory effects at both systemic and plaque levels, especially in diabetic models of atherosclerosis, through improved glycemic control and enhanced insulin sensitivity." (PMID 41302207, 2025). "It possesses anti-inflammatory properties, enhances insulin sensitivity, prevents atherosclerosis, offers cardioprotection, and regulates apoptosis while inhibiting cell proliferation in the myeloid lineage." (PMID 40292250, 2025). "Metabolic and cardiovascular pathways, including lipid and atherosclerosis and adipocytokine signaling, highlight links to lipid metabolism, insulin sensitivity, and cardiovascular health." (PMID 40242450, 2025). "NMN has been shown to reduce serum lipid levels, decrease high-fat diet-induced hepatic lipid deposition, improve glucose tolerance, and enhance insulin sensitivity, which were also related to the development of atherosclerosis." (PMID 40143060, 2025). "SO markedly hastens the initiation and progression of atherosclerosis via various mechanisms, including hormonal imbalances, deregulation of adipokines and myokines, insulin resistance, chronic low-grade inflammation, and abnormalities in lipid metabolism." (PMID 41303183, 2025). "SLD and chronic metabolic disorders, such as T2DM and HTN, share common pathophysiological mechanisms, including insulin resistance and chronic inflammation, which ultimately contribute to the development of atherosclerosis and CVD." (PMID 40650668, 2025). "Therapeutic agents that improve insulin sensitivity, such as PPAR-γ agonists (e.g., pioglitazone), can help restore insulin signaling balance in VSMCs, reducing pathological proliferation and migration and potentially slowing atherosclerosis progression." (PMID 40564010, 2025). "Lactate activates GPR81 and inhibits lipolysis in adipocytes through insulin-induced antilipolysis, thus reducing the concentration of fatty acids in plasma, which is positively correlated with atherosclerosis." (PMID 40076419, 2025). "Instead, it creates a “pathological network” that promotes atherosclerosis through the interaction of multiple systems, including hormonal and muscle-fat factor imbalances, insulin resistance, chronic inflammation, and lipid metabolism disturbances." (PMID 41303183, 2025). "Potentially, a higher Kyn/Trp ratio, induced by IFN‐γ, is an indicator of inflammatory processes related to atherosclerosis, or related to impairments in insulin sensitivity." (PMID 39308420, 2025).
atherosclerosis (continued). "We conclude that besides its beneficial effects on insulin sensitivity, systemic inflammation, and atherosclerosis, the deletion of MMP12 improves brown adipose tissue function in cardiometabolic conditions." (PMID 41308745, 2025). "Impaired insulin signaling has deleterious effects on the endothelium and vascular smooth muscle cells, enhancing endothelial dysfunction and the progression of atherosclerosis." (PMID 40149860, 2025). "PPARG, a ligand-activated transcription factor, plays critical roles in adipocyte development, insulin sensitivity, lipid metabolism, and atherosclerosis in tissues such as adipose, macrophages, intestines, and ovaries." (PMID 40028534, 2025). "Additional mechanisms linking low SMD to increased mortality is impaired insulin sensitivity and atherosclerosis development." (PMID 41187122, 2025). "KEGG pathways analysis revealed enrichment in signaling pathways related to insulin action, growth/development, cellular senescence, lipid/atherosclerosis, Th17 cell differentiation, insulin resistance, autophagy, and apoptosis." (PMID 41282288, 2025). "This condition results in elevated blood glucose levels and excessive insulin secretion, potentially triggering abnormal inflammation and lipid metabolism, thus accelerating atherosclerosis development." (PMID 38755609, 2024). "Previous studies have shown that Ilex paraguariensis (yerba mate) aqueous extracts inhibited the progression of atherosclerosis and decreased body weight, visceral fat, serum lipids, glucose, leptin, and insulin levels in HFD-fed-rats." (PMID 39065815, 2024). "Disturbed insulin signaling within the cells lining the innermost layer of blood vessels, which play a role in atherosclerosis, including endothelial cells, vascular smooth muscle cells, and macrophages, is thought to be a contributing factor." (PMID 38572476, 2024). "The KEGG enrichment analysis identified potential targets in several pathways, including alcoholic liver disease, lipid and atherosclerosis-related pathways, insulin resistance, TNF signaling pathway, etc." (PMID 39372201, 2024). "It prevents atherosclerosis by lowering total cholesterol, triglycerides, and insulin levels in rat blood." (PMID 39203723, 2024). "Several pathways directly related to CAD such as Insulin signaling pathway, diabetic cardiomyopathy pathway, lipid and atherosclerosis pathway were observed to be regulated by miR-128-3p." (PMID 38789551, 2024). "Metformin treatment resulted in positive changes in the adipocyte morphology and regulated the methylation of several genes related to atherosclerosis, insulin, and fatty acids signaling pathways." (PMID 38256201, 2024). "Among these markers, TNF-α plays a pivotal role in the pathogenesis of various diseases, particularly chronic inflammation that links rheumatoid arthritis, atherosclerosis, and impaired insulin sensitivity." (PMID 38397603, 2024). "IR disrupts insulin signaling, promotes chronic systemic inflammation, reduces insulin sensitivity, and increases foam cell formation, thereby accelerating atherosclerosis and advanced plaque formation." (PMID 38954387, 2024). "In contrast, high levels of IGFs can negatively contribute to cancer cell growth and other diseases like Alzheimer’s, atherosclerosis, insulin dysregulation, and disorders of the endocrine system." (PMID 39593747, 2024). "The HDL particles have a beneficial effect against atherosclerosis as well as the capacity to induce insulin secretion." (PMID 39330521, 2024). "The mechanism by which sarcopenic obesity accelerates atherosclerosis is a complex process that is not fully understood; however, insulin resistance and inflammatory cytokines produced by the adipose tissue are major contributing factors." (PMID 39458058, 2024). "Ultimately, plant fiber diets benefit cardiovascular health by lowering dyslipidemias, increasing insulin sensitivity, reducing inflammation, preventing atherosclerosis, and improving metabolic health." (PMID 39314563, 2024).
atherosclerosis (continued). "The corresponding significant enriched signaling pathways were atherosclerosis, insulin signaling, and fatty acids metabolism." (PMID 38256201, 2024). "Therefore, the underlying mechanism could be linked to oxidative stress triggered by insulin resistance and pro-inflammatory cytokines, resulting in arterial stiffness, emphasizing a significant association between sarcopenic obesity and atherosclerosis, ultimately causing CVD." (PMID 39458058, 2024). "The KEGG pathway analysis identified significant enrichment in pathways related to lipid and atherosclerosis, insulin resistance, and Phosphoinositide 3-kinase (PI3K)-Akt signaling." (PMID 39598338, 2024). "Adipose tissue, functioning as an active endocrine organ, secretes substantial quantities of cytokines and bioactive mediators, influencing insulin sensitivity, inflammation, coagulation, and ultimately, atherosclerosis." (PMID 39086898, 2024). "HDL-C affects the cardiovascular system through multiple mechanisms, including anti-inflammatory and antioxidant effects, reversing cholesterol transport to reduce the atherosclerosis burden, and increasing insulin sensitivity." (PMID 39588068, 2024). "High-fiber PBDs are linked to increased insulin sensitivity, lower total and LDL cholesterol levels, and reduced inflammation, which diminish atherosclerosis progression and CVD incidence." (PMID 39314563, 2024). "Several studies have shown that insulin resistance restricted to the endothelial cell (EC) lining of the vasculature leads to accelerated atherosclerosis." (PMID 39401163, 2024). "It is possible that iHSP70 and eHSP70 are affected by the progress of atherosclerosis and the length of the insulin resistance period in individuals." (PMID 37238736, 2023). "It has also been suggested that insulin resistance and the inflammatory response in the gallbladder and kidneys promote atherosclerosis and vasculopathy in the blood vessels." (PMID 36983309, 2023). "For example, t10,c12-CLA worsens atherosclerosis and insulin sensitivity by inhibiting the expression of peroxisome proliferator-activated receptor gamma (PPARγ) and liver X receptor alpha (LXRα)." (PMID 37367916, 2023). "On the contrary, c9,t11-CLA and t9,t11-CLA reduce atherosclerosis and improve insulin sensitivity by enhancing PPARγ and LXRα." (PMID 37367916, 2023). "In contrast, selective inhibition with myriocin decreased ceramide levels, alleviated obesity-derived atherosclerosis, enhanced insulin sensitivity, and decreased body weight." (PMID 38274826, 2023). "The administration of doxycycline could be able to simultaneously prevents preclinical atherosclerosis and the loss of pancreatic islets and β cells in individuals chronically fed a high-fat diet, while possibly increasing the ability of β cells to release insulin into the blood." (PMID 36979696, 2023). "Some plant-based dietary supplements such as grape products and cinnamon have been shown to improve insulin resistance and atherosclerosis, probably by mitigating antioxidative stress and the inflammatory response." (PMID 37568221, 2023). "Elevated levels of IR and insulin activate vascular endothelial Na+ channels, leading to decreased NO utilization and atherosclerosis." (PMID 38075069, 2023). "For upregulated genes, the top 5 KEGG-enriched pathways with the lowest adjusted P value were glutathione metabolism, ferroptosis, fluid shear stress and atherosclerosis, FoxO signaling pathway, and insulin signaling pathway." (PMID 38076131, 2023). "Aerobic physical activity is associated with lower blood pressure, reduced inflammation, insulin sensitivity, and improved lipid profile and endothelial function, leading to lower risks of atherosclerosis and thrombosis." (PMID 37316812, 2023). "In previous literature, adiponectin, an adipose tissue–secreted cytokine, has been reported to show improvements in insulin sensitivity, glucose regulation, lipid metabolism, and reduce atherosclerosis." (PMID 36297122, 2022).
atherosclerosis (continued). "Cumulating studies have revealed that adiponectin can increase insulin sensitivity, suppress inflammation, and counteract atherosclerosis." (PMID 35957678, 2022). "Non-clinical and clinical data clearly highlight the potential of ligands for these channels, especially natural compounds such as capsaicin/capsinoids and cinnamaldehyde, to treating the various aspects of MS, from insulin resistance to atherosclerosis." (PMID 35455971, 2022). "Insulin signaling also plays an important role in nitric oxide production, which is considered a strong vasodilator and a substance with anti-atherosclerosis properties." (PMID 35885586, 2022). "The mechanism lies in that obese children present increased oxidative stress and impaired inflammation and insulin sensitivity, which in turn results in similar impaired endothelial dysfunction and early signs of atherosclerosis." (PMID 35379317, 2022). "TZDs, the insulin-sensitizing agents, are known to have a strong protectiveeffect on atherosclerosis-driven events such as cardiac or cerebrovasculardisease." (PMID 39077692, 2022). "While it is possible that a much higher level of LDL-C is needed to cause fatty streaks in mice as compared to humans, these observations assign a stronger role for insulin sensitizers in the prevention of atherosclerosis." (PMID 35457157, 2022). "Targeting TRAF6 MATH is reported to improve insulin sensitivity in obese mice, improve heart function in mouse models of non‐ischemic cardiac failure, reduce atherosclerosis, and inhibit osteoclastogenesis and bone resorption." (PMID 36305766, 2022). "Adiponectin is important in transporting glucose, regulating lipid metabolism and improving insulin sensitivity, which elicit an anti-inflammatory role in inhibiting the formation of atherosclerosis." (PMID 35114975, 2022). "Middle Eastern immigrants constitute a growing proportion of the European population and compared to native Swedes are more insulin resistant, which can contribute to atherosclerosis." (PMID 36309585, 2022). "Tissue localized RAS is called tissue RAS, studies have shown that the local RAS is thought to be involved in a variety of physiological and pathological processes, such as insulin secretion, glomerulosclerosis, nephritis, and atherosclerosis." (PMID 36387894, 2022). "Sodium-glucose co-transport 2 inhibitors exert anti-atherosclerotic properties attenuating inflammatory factors, alleviating inflammation, mitigating insulin resistance, and reducing stress on vessels, inhibiting atherosclerosis development and progression." (PMID 36148061, 2022). "Through the evidence of this study, for elderly tennis participants, it can provide the relationship between the amount of tennis participation and atherosclerosis, metabolic biomarkers, and insulin sensitivity." (PMID 33573269, 2021). "Thus, lower insulin sensitivity might cause silent lacunar infarcts via atherosclerosis." (PMID 34702849, 2021). "ERα plays an important role in energy metabolism, insulin resistance, fat accumulation or atherosclerosis." (PMID 34089761, 2021). "Of relevance to atherosclerosis, in insulin-resistant states, insulin’s ability to activate the IR signaling pathway in vascular smooth muscle cells is impaired, leading to decreased nitric oxide generation and accelerated atherogenesis." (PMID 33400689, 2021). "In the following paragraphs we will discuss in detail PON2 involvement in atherosclerosis (Section 6.1), cancer (Section 6.2), insulin sensitivity (Section 6.3), and neurodegeneration (Section 6.4)." (PMID 33562328, 2021). "Irisin is surmised to participate in atherosclerosis by some indirect ways such as influencing insulin release." (PMID 34276559, 2021). "In summary, APOA4 can protect against lipid peroxidation, inhibit the progression of atherosclerosis, and enhance insulin secretion in OSA patients." (PMID 34185819, 2021).
atherosclerosis (continued). "Loss of skeletal muscle reduces the mass of the primary tissue responsible for insulin-mediated glucose disposal and promotes insulin resistance, which plays a key role in the pathogenesis of atherosclerosis." (PMID 33855037, 2021). "For example, we found that the patients receiving insulin therapy had higher levels of TC and LDL-C, which are among the most important risk factors for atherosclerosis." (PMID 33598483, 2021). "PCR array analysis revealed the modulatory effect of DHA and insulin on the expression of atherosclerosis-related genes pre-treated with palmitic acid compared to the control group (p < 0.05)." (PMID 33602249, 2021). "Metabolomic studies in humans have supported previous findings into the pathomechanisms of CVD, namely atherosclerosis, apoptosis, inflammation, oxidative stress, and insulin resistance." (PMID 34564437, 2021). "Disturbance to the insulin signaling pathway in endothelial cells is present in vascular diseases such as atherosclerosis, chronic hypertension and preeclampsia." (PMID 34696680, 2021). "Another important topic of interest within the field of atherosclerosis, for which the role of serum levels of insulin and glucose are even more elusive, pertains to plaque composition." (PMID 31958313, 2020). "Pre-clinical studies have shown beneficial effects of glycosphingolipid synthesis in improving insulin sensitivity and atherosclerosis." (PMID 32033078, 2020). "In the same line, a recent animal study that examined the role of insulin in atherosclerotic plaque reported the protective effect of insulin on atherosclerosis." (PMID 31958313, 2020). "Until now, most of the evidence linking insulin and glucose to atherosclerosis comes from studies in which atherosclerotic cardiovascular clinical endpoints, such as ischemic heart disease or ischemic stroke, were investigated." (PMID 31958313, 2020). "Adiponectin has many important physiological functions, including regulate energy metabolism, increase in insulin sensitivity, promotion of its production, and even effects on atherosclerosis and angiogenesis." (PMID 33327229, 2020). "SARS-CoV-2 interactome strongly connects with the complete ACE2 network through INS, CDK4 (Cyclin-Dependent Kinase 4), CCL2, and ALB (Albumin), all of them associated with atherosclerosis processes." (PMID 33233425, 2020). "The pathways related to metabolism included AGE-RAGE signaling pathway in diabetic complications, Fluid shear stress and atherosclerosis and Insulin resistance." (PMID 32863886, 2020). "This study did not evaluate IDE and TGF-β1 expression but LGF administration significantly reduced plasmatic levels of insulin in an experimental model of atherosclerosis in mice, and modulated the synthesis of TGF-β1 in bile duct-ligated rats." (PMID 33276671, 2020). "We have previously reported that human IGFBP-1, when overexpressed in mice, leads to vascular insulin sensitization; increased nitric bioavailability; reduced atherosclerosis; and enhanced vascular repair." (PMID 32190801, 2020). "Previously, animal studies demonstrated also that impaired insulin signaling by genetic modification accelerated atherosclerosis." (PMID 31958313, 2020). "At the same time, insulin has a controversial role in atherosclerosis, since it confers protection to ECs by inducing eNOS production." (PMID 32816039, 2020). "In this study, the insulin effect was tested on atherosclerosis in a mouse model, and insulin was found to decrease the plaque burden and increased plaque stability via nitric oxide synthase (NOS) mechanisms." (PMID 31958313, 2020). "It is reported to play protective roles in a variety of disease models, including acute lung injury, peritonitis, wound infection, insulin resistance and atherosclerosis models." (PMID 32317985, 2020). "Nobiletin regulated liver biomarkers by increasing hepatic and peripheral insulin sensitivity, improving glucose tolerance, and protecting against the development of atherosclerosis." (PMID 32977511, 2020).